AKT2 (AKT serine/threonine kinase 2)
Diseases named in the same sentence as AKT2 in open-access papers (continued):
Sharing a sentence is not in itself a finding about the gene and the disease.
breast cancer (continued). "AKT2 knockdown inhibited the chemotaxis of breast cancer cells, whereas knockdown of AKT3 resulted in reduced expression of HER2 and HER3 and upregulation of ER-alpha, resulting in an increased responsiveness of murine model cells to antiestrogen." (PMID 35892586, 2022). "According to the existing literature, AKT2 is the target of miR-615-5p in pancreatic cancer and breast cancer." (PMID 35528616, 2022). "AKT has three isoforms, AKT1, AKT2 and AKT3, with highly conserved domain structure, which are associated with breast cancer progression and play different roles in breast cancers." (PMID 34503444, 2021). "Like AKT1, the role of the AKT2 isoform in breast cancer is complex and there are conflicting reports in the literature." (PMID 33498407, 2021). "In opposition, AKT2 has been shown to promote metastasis by enhancing migration and invasion of breast cancer cells mediated by a regulation of F-Actin, vimentin, and integrin β1." (PMID 33670586, 2021). "Dysregulation of p-Akt, Akt2, and PTEN was observed in mammary tumor samples, but only PTEN dysregulation was associated with PIK3CA H1047R mutation." (PMID 34359206, 2021). "It was then realized that Akt1 and Akt2 have opposite roles in breast cancer initiation and progression." (PMID 34298660, 2021). "Twist, a transcription factor for EMT, was shown to mediate invasion in MCF-7 and MBA-MB-453 cells by transactivating the Akt2 promoter and there was a correlation between Akt2 and Twist expression in late-stage breast cancers." (PMID 34298660, 2021). "It has been reported Akt2 was amplified in 3% of breast cancers and Akt3 is frequently amplified in TNBC." (PMID 34298660, 2021). "Dietary fatty acids, such as linoleic acid and oleic acid were also shown to promote migration and invasion in breast cancer cells via Akt2." (PMID 34298660, 2021). "These actions of Akt2 can be partly responsible for increased glucose uptake and the reprogramming of metabolism seen in breast cancer." (PMID 34298660, 2021). "Evidence supports that radiation increases phosphorylated AKT1 and AKT2 in the breast cancer MCF7 mammospheres CD44+/CD24−/low-expressing cells, whereas the inhibition of the AKT signaling pathway sensitizes MCF7 mammosphere cells to ionizing radiation." (PMID 34217266, 2021). "Based on TCGA dataset, Akt3 is most amplified followed by Akt2 and amplification of Akt1 was least among Akt isoforms in breast cancer." (PMID 34298660, 2021). "A balance between Akt1 and Akt2 decided the invasiveness and metastasis of primary and metastatic breast cancers by differential regulation of miR-200." (PMID 34298660, 2021). "While different studies revealed different results regarding the involvement of AKT1 and AKT2 in mammary carcinomas, AKT3 dysfunctions are often correlated with triple negative breast cancer." (PMID 34199634, 2021). "The PI3K/AKT pathway is a well-established oncogenic pathway, and AKT1 and AKT2 have repeatedly been shown to differentially regulate breast cancer cell proliferation and invasion." (PMID 32201539, 2020). "Recently, it was also shown that TWIST1 is phosphorylated by Akt, in turn, TWIST1 transcriptionally upregulates AKT2 gene in breast cancer cells, and this induction leads to invasion and migration of breast cancer cells." (PMID 32922123, 2020). "In contrast, constitutively active Akt2 slows breast cancer development but accelerates invasion and recurrence in this model." (PMID 33110146, 2020). "Akt1 gene amplification was found in breast, colon, pancreatic, gastric, esophageal, ovarian, and thyroid cancers, and glioblastoma while amplification of Akt2 occurred in pancreatic, ovarian, and breast cancers." (PMID 32106627, 2020). "Germline and systemic Akt2 ablation also showed opposing effects on mammary cancer metastasis as murine germline deletion impaired metastasis but systemic loss of Akt2 enhanced metastasis." (PMID 33276499, 2020).
breast cancer (continued). "Ablation of single AKT isoforms in oncogene-driven mouse models of breast cancer has revealed more complex roles for AKT1 and AKT2 in regulating mammary tumour progression." (PMID 33276499, 2020). "AKT1 expression is higher than AKT2 during the later stages of tumour development in oncogene-driven murine mammary cancer models." (PMID 33276499, 2020). "In breast cancer, inhibition of AKT2 can not only effectively prevent the transformation of mesenchymal non-cancer stem cells (non-CSC) into epithelial cells but also reduce the invasive and colony formation abilities of non-CSC and CSC." (PMID 32873299, 2020). "Akt2 overexpression was present in 40% of hepatocellular carcinoma and 57% in colorectal cancers, while Akt3 overexpression was found in prostate and breast cancers." (PMID 32106627, 2020). "AKT2 has been discovered to be overexpressed in human cancer tissues, including lung cancer, breast cancer, and colon cancer tissues." (PMID 32873299, 2020). "A striking example are the roles of AKT1 and AKT2 in breast cancer where AKT2 enhances migration and invasion, whereas AKT1 inhibits these processes." (PMID 33045011, 2020). "In line, highly invasive clones of a breast cancer cell line show elevated levels of AKT2 expression and pAKT2." (PMID 31752925, 2019). "The transcription factor Twist specifically upregulates AKT2 expression by transactivation of its promotor and therefore causes EMT-mediated migration, invasion and metastasis as an early process in breast cancer progression." (PMID 31752925, 2019). "AKT2 is mainly found in pancreatic cancer, ovarian cancer, and breast cancer, and is related to the continued survival of tumor cells." (PMID 31160577, 2019). "AKT1 and AKT3 are associated with breast cancer invasion, and PTEN-deficient tumors depend on AKT2 for maintenance and survival." (PMID 30837881, 2019). "A couple of studies confirmed the pro-migratory role of AKT2 and dealt with possible mechanisms behind the crucial role of AKT2 in breast cancer migration, invasion and metastasis." (PMID 31752925, 2019). "Using fluorescent CSC models driven by the expression of ALDH1A 1(aldehyde dehydrogenase 1A1), we confirmed this dynamic phenotypic change in MDA-MB-231 breast cancer cells and to identify Serine/Threonine Kinase 2 (AKT2) as an important player in the process." (PMID 31357505, 2019). "AKT1 mediates this effect through a negative regulation of receptor tyrosine kinases like EGFR, whereas AKT2 is a suppressor of the pro-migratory miR-200 family like in breast cancer cells." (PMID 31752925, 2019). "Roughly summarized, AKT1 is important for breast cancer initiation and growth of the primary tumor, whereas AKT2 plays a pivotal role in progression of breast cancer by formation of metastases." (PMID 31752925, 2019). "Gene amplifications of AKT2 occur in 2.8% up to 4% of human breast carcinomas, although the number of breast cancer samples with amplified AKT2 is lower than in ovarian cancer." (PMID 31752925, 2019). "As a consequence of the AKT activation, the cells acquire a higher survival under hypoxic environment and thus AKT2 promotes tumorigenic properties of breast cancer cells." (PMID 31752925, 2019). "The investigation of AKT isoform expression and activation in human breast cancer probes and breast cancer cell lines detected expression of AKT1 and AKT2 in all breast cancer cell lineages with a higher abundance in the luminal breast cancer subtype." (PMID 31752925, 2019). "For instance, Akt1 is essential for the propagation of breast cancer, whereas ablation of Akt2 inhibits apoptosis and delays tumour involution." (PMID 29890731, 2018). "For example, preclinical data suggested that AKT2 promotes metastasis in ovarian and breast cancer cell models while AKT1 was proposed to inhibit the migration and metastasis of breast cancers." (PMID 29506489, 2018).
breast cancer (continued). "PM were loaded with a siRNA against AKT2, an important oncogene involved in breast cancer tumorigenesis, with a special role in CSC malignancy." (PMID 29667444, 2018). "Our data showed a prominent role of Akt1, and to a lesser extent, Akt2, in such processes in TICs derived from breast cancer cells." (PMID 29518912, 2018). "For example, AKT1 has been demonstrated to suppress while AKT2 promotes breast cancer cell migration and invasion in vitro." (PMID 30012111, 2018). "In breast cancer, Akt1 appears to play a fundamental role in the propagation of such tumours, whereas ablation of Akt2 inhibits apoptosis and delays tumour involution." (PMID 29518912, 2018). "Of 3 members (AKt1, AKt2, and AKt3) of the AKt family, AKt1 and AKt2 are important signaling molecules related to a diabetic phenotype such as IR; at the genomic level, each is amplified in various cancers including breast cancer." (PMID 29023587, 2017). "This is consistent with the established role for AKT1 in inhibiting and AKT2 in promoting breast cancer cell migration and metastasis." (PMID 28082369, 2017). "It has been reported that the expression levels of AKT2 are related to the malignant degree of cancers, including osteosarcoma, breast cancer, lung cancer and other cancers." (PMID 29051585, 2017). "The present study was designed to analyze the specific role and signaling of AKT1 and AKT2 in regulating the different stages of breast cancer progression in two human ductal breast cancer cell lines growing in culture and in xenografts." (PMID 28287129, 2017). "AKT1 localizes to the cytoplasm in a number of human breast cancer cell lines, whereas AKT2 is present in mitochondria and the cytoplasm and AKT3 exhibits a nuclear and nuclear membrane distribution." (PMID 28082369, 2017). "We provide experimental and clinical evidences that it is mainly AKT2 overexpression that is related to disease progression and has a worse prognostic value in breast cancer." (PMID 28287129, 2017). "Our results in breast cancer cell lines show that even though AKT1/AKT2 dual silencing reduces cell proliferation, it surprisingly enhances cell migration and invasion." (PMID 28287129, 2017). "Regarding AKT1 and AKT2 studies, several transgenic mouse models with mammary carcinomas have been developed, and they showed diverse results." (PMID 28287129, 2017). "AKT2 expression levels were inversely correlated with miR-124 expression levels in human breast cancer specimens." (PMID 27175587, 2016). "Our present study demonstrates a distinct regulatory role of miR-564 in breast cancer progression by direct targeting of a network of genes, namely AKT2, GNA12, GYS1 and SRF that leads to simultaneous inhibition of PI3K and MAPK pathways." (PMID 27600857, 2016). "Ezrin is a cytoskeleton and signaling molecule that regulates cell adhesion, migration, and invasion, whereas Akt2 is a kinase involved in invasiveness of breast cancer cells and is able to phosphorylate ezrin." (PMID 27314390, 2016). "This reflects the frequent activation of receptor tyrosine kinases, activating mutations in PI3KCA and AKT1, as well as overexpression of AKT2 or AKT3 and inactivation of the tumor suppressor gene PTEN in breast cancer." (PMID 26741489, 2016). "Several studies have suggested that Twist1 is associated with pathways in the EMT process such as Wnt/β-catenin signaling, PI3K/AKT/TGF-β signaling, AKT2 signaling, and NF-κB signaling in breast cancer cells." (PMID 27494849, 2016). "Since opposing effects of AKT1 and AKT2 were described in breast cancer cell migration, AKT1 suppressing invasion and AKT2 enhancing it, we analyzed phosphorylation of AKT1 and AKT2, in addition to T308 in the RUNX2 knocked down melanoma cell lines." (PMID 27102439, 2016). "In a MMTV-ErbB2/Neu model of breast cancer, Akt1 ablation inhibited tumor formation, while Akt2 ablation enhanced mammary tumor growth." (PMID 27533079, 2016).
breast cancer (continued). "For example, overexpression of AKT1 was shown to inhibit motility, whereas overexpression of AKT2 promotes motility and migration in breast cancer cells, the latter resulting in increased formation of metastases." (PMID 26741489, 2016). "In cancer cell migration and invasion, Akt1 and Akt2 appear to act antagonistically; thus, Akt1 suppresses, while Akt2 promotes, breast cancer cell migration and metastasis." (PMID 25575302, 2015). "Second, AKT signalling is often dysregulated in breast cancer and AKT2 has been identified as a driver gene in mammary tumourigenesis." (PMID 26070602, 2015). "These AKT isoforms seem to mediate different functions in cancer pathophysiology; for example, AKT1 appears to promote mammary tumor induction, whereas AKT2 promotes metastasis in previous reports." (PMID 26338103, 2015). "In regards to breast cancer, studies have focused on the opposing functions of Akt1 and Akt2 on cell migration and invasion." (PMID 25069766, 2014). "In contrast, while AKT2 has been shown to promote apoptosis in lung cancer cells, it can promote invasion and metastasis of breast cancer cells." (PMID 24946858, 2014). "Future studies using Akt inhibitors for the treatment of breast cancer should employ Akt inhibitors that target both Akt1 and Akt2 in combination with inhibitors that target additional signaling pathways such as the MAPK signaling pathway." (PMID 23919516, 2013). "The levels of Akt1 were undetectable in MTB-IGFIR/Akt1−/− mammary tumors while the levels of Akt2 were similar in MTB-IGFIR mammary tumors, and mammary tumors from MTB-IGFIR/Akt1−/− mice." (PMID 23919516, 2013). "Despite the loss of Akt1 or Akt2, the mammary tumors from MTB-IGFIR/Akt1−/− and MTB-IGFIR/Akt2−/− mice had levels of phosphorylated Akt similar to the mammary tumors that developed in MTB-IGFIR mice." (PMID 23919516, 2013). "In MDA-MB-231 human breast cancer cells, which express low levels of activated Akt, the overexpression of constitutively active forms of Akt1 or Akt2 inhibited cell proliferation and migration with little effect on apoptosis." (PMID 23919516, 2013). "Akt1 and Akt2 levels were stably ablated in mammary tumors of MTB-IGFIR transgenic mice by crossing MTB-IGFIR transgenic mice with either Akt1−/− or Akt2−/− mice." (PMID 23919516, 2013). "Mammary tumors with normal levels of Akt1 and Akt2 had similar levels of the IGF-IR as mammary tumors null for Akt1 or null for Akt2." (PMID 23919516, 2013). "In particular, AKT1 and AKT2 opposing functions on migration of breast cancer epithelial cell lines have been firmly established." (PMID 23165443, 2013). "Specific gain of function of Akt2 promotes migration and invasion in breast cancer epithelial cells, whereas Akt1 is mostly involved in cell proliferation and growth." (PMID 32309540, 2013). "Akt2 overexpression enhances invasive potential of breast cancer cells and their ability to metastasize, Akt2 expression and activity suppress anoikis and apoptosis caused by deprivation of nutrients." (PMID 22842582, 2012). "Conclusively, the group of Muller demonstrated that AKT1 induced tumor growth, while AKT2 promotes metastasis of ErbB2-induced breast cancer in vivo." (PMID 23167739, 2012). "HER2-positive breast cancer cell lines and primary tumours were found to have high expressions of Akt1, Akt2 and their activated forms." (PMID 22842582, 2012). "A number of studies examined the role of Akt, especially the Akt1 and Akt2, in breast cancer and its prognostic and predictive value." (PMID 22842582, 2012). "For example, AKT1 knockdown induces cell migration and EMT in breast cancer cell lines, while AKT2 knockdown suppresses these behaviors." (PMID 22666248, 2012). "Akt1 and Akt2 were expressed in all tested breast cancer cell lines, but Akt3 was detectable only in MDA-MB-231 cells." (PMID 21362200, 2011).
breast cancer (continued). "Our data demonstrates that Akt2 is the most critical player in the regulation of cell proliferation and survival among the three isoforms, at least in the breast cancer model examined." (PMID 21297943, 2011). "Our data, thus, raises the possibility that Akt2 can be an effective anticancer target for the control of (breast) cancer." (PMID 21297943, 2011). "By systematically studying Akt-ablated MDA-MB231 breast cancer cells with isoform-specific siRNA, we here show that Akt2 is the most relevant isoform to cell proliferation and survival in our cancer model." (PMID 21297943, 2011). "Since EF1α is often overexpressed in breast cancer, the consequences of EF1α increased levels for proliferation, survival and invasion will likely depend on the relative concentration of Akt1 and Akt2." (PMID 19646290, 2009). "A recent report suggests that Akt2 contributes to breast cancer metastasis via protein kinase C (PKC)-ζ." (PMID 19430575, 2008). "It has been reported that Akt2 is amplified in 3% of breast cancers and is frequently activated in primary human breast carcinoma." (PMID 19430575, 2008). "AKT2, on the other hand, plays a critical role in both tumor development and the reprogramming of glucose metabolism, and it has been shown to be overexpressed in multiple cancer types, including breast cancer." (PMID 41300329, 2025). "The AKT1 and AKT2 isoforms play dominant roles in breast cancer." (PMID 41408399, 2025). "However, context and cell-type specific effects have to be considered, as seen for example for Akt1, which is pro-migratory in untransformed fibroblasts but anti-migratory in breast cancer cells, or for Akt2 showing the opposite effects in these cell types." (PMID 38291468, 2024). "In many cases, breast cancer metastasis may be under the control of balance between Akt1 and Akt2 and their link with MiR-200/Zeb/E-cadherin axis." (PMID 38002001, 2023). "Ablation of AKT1 or AKT2 in murine breast cancer models and of AKT1 or AKT2 in human breast cell lines was associated with suppression of tumor progression and cell-cycle progression, increased apoptosis, and an overall reduced metastatic potential of target cells." (PMID 35892586, 2022). "However, Akt1 inhibits breast cancer migration and metastasis, while Akt2 exhibits an opposite phenomena." (PMID 36180910, 2022). "Interestingly, TWIST1 transcriptionally upregulated AKT2 in breast cancer cells, leading to increased migration, invasion, and resistance to paclitaxel." (PMID 35242497, 2022). "Accumulating evidence revealed that, in breast cancer as in other solid tumors, Akt2 levels may be modulated by several miRNAs, including miR-615, which was reported to reduce the expression of Akt2 in TNBC cells." (PMID 35743776, 2022). "Despite that a consensus regarding the isoform-specific functions of Akt was not reached even within a specific subtype of breast cancer, Akt2 was associated with tumor progression by increasing cell migration, invasion, and metastasis." (PMID 35743776, 2022). "Notably, AKT2 is the main regulator that promotes a higher survival rate of breast cancer cells under hypoxia because hypoxia induces the expression of AKT2, but not AKT1 or AKT3." (PMID 35111368, 2022). "WDR26, a WD40 protein that is overexpressed in highly malignant breast cancers and is associated with poor survival of breast cancer patients, selectively bound to Akt2 and not Akt1." (PMID 34298660, 2021). "Knockdown of Akt1 and Akt3 in ErbB2-positive Erα-negative mouse mammary tumor C4 cells caused a substantial decrease in cell proliferation whereas Akt2 knockdown had only a modest effect." (PMID 34298660, 2021). "While Akt1 still inhibits breast cancer cell migration, Akt2 promotes breast cancer cell migration." (PMID 34419139, 2021).